PLAU (plasminogen activator, urokinase)
Diseases named in the same sentence as PLAU in open-access papers (continued):
Sharing a sentence is not in itself a finding about the gene and the disease.
tumor (continued). "Moreover, the overexpression of PLAU in tumor epithelial cells facilitates its interaction with the receptor PLAUR, predominantly expressed on macrophages, thereby influencing the abnormal epithelial–immune interactome in HNSCC." (PMID 39511134, 2024). "PLAU overexpressed in tumor epithelia could increase its binding with the receptor PLAUR, expressed mainly on macrophages, to ultimately influence the aberrant epithelial–immune interactome in HNSCC." (PMID 39511134, 2024). "Conversely, the unique pathways specific to each group, such as APRIL in the immune-active group and PLAU in the immune-suppressed group, may play a vital role in regulating T cell infiltration within the tumor." (PMID 39329702, 2024). "Notably, additional ECM invasion-related proteases, including MMP2, 9, 13 and PLAU, were also reduced, to varying degrees, in siSE-LbL-treated tumor nodules." (PMID 38437557, 2024). "Our findings supported that PLAU overexpressed in tumor tissue could interact with PLAUR to regulate the crosstalk between malignant epithelial cells and immune cells, presumably favoring immune escape in HNSCC." (PMID 39511134, 2024). "While upregulation of PLAU is associated with upregulation of MMP activity and promotion of tumor cell invasion, the observed downregulation of these genes may explain the lack of invasion in the presence of upregulated MMP." (PMID 36674745, 2023). "In addition, except for TIMP1 (P > 0.05), the expression levels of INHBA (P < 0.05), LAMC2 (P < 0.05), PLAU (P < 0.05) and TGFβ1 (P < 0.05) were significantly different between tumour and normal samples." (PMID 37325056, 2023). "Moreover, MRC2, OLFML2B, and PLAU were differentially and highly methylated between tumor and normal tissues as well as between genders, races and tumor grads." (PMID 37340445, 2023). "Thus, our data indicating PLAU expression is activated by DSCAM-AS1 also point to a tumor-promoting role of this lncRNA in this context." (PMID 35885035, 2022). "Dysregulation of PLAU is often accompanied by various cancers, and inhibition of PLAU expression could suppress tumor growth." (PMID 36077151, 2022). "In addition, CD8+ T cells kill PTC tumor cells, and PLAU expression was negatively correlated with CD8+ T cell infiltration, suggesting a poor prognosis, which is also consistent with our findings." (PMID 35141223, 2022). "PLAU expression was detected not only in tumor cells, but also in fibroblasts and myeloid cells." (PMID 36397035, 2022). "PLAU could increase cell adhesion and migration during metastasis and proliferation of tumor cells, which may explain our finding that elevated expression of PLAU in node metastasis tumors." (PMID 33520474, 2021). "The co-expression network and scores of tumor immune microenvironment were established and analyzed in this study as well, which could be interpreted to the possible mechanism of PLAU’s role in HNSCC patients." (PMID 33520474, 2021). "Overexpressed PLAU could increase cell adhesion and migration, which is important in the metastasis and proliferation for tumor cells." (PMID 35046992, 2021). "PLAU encodes an enzyme that is involved in ECM proteolysis, tumor cell migration and proliferation." (PMID 34641959, 2021). "In consideration that the EMT process was significantly enriched by PLAU and its co-expression genes, it is expected that PLAU might play a role in tumor invasion." (PMID 34093649, 2021). "PLAU transcription levels were significantly higher in HNSCC tumor tissues among different studies." (PMID 34093649, 2021). "In addition, IL8 subsequently upregulates PLAU expression and secretion from tumor cells, which further promotes the progression of ESCC." (PMID 33574243, 2021). "More importantly, by comparing the extent of protein changes, the overexpressed SERPINE1 and PLAU are the most promising markers, and its detection could help to identify tumor cells in tissues." (PMID 30937621, 2019). "PLAU also plays crucial roles in tumor invasion and metastasis." (PMID 29351231, 2018).
tumor (continued). "The third connection including TGM2, IL1B, and PLAU was suggested to be tumor invasion." (PMID 20142997, 2010). "Collectively, these data suggest that the overexpressed PLAU in tumor epithelia could interact with its receptor PLAUR located on the surface of immune cells (especially macrophages), to influence the interaction mode of aberrant epithelial cells and immune cells in HNSCC." (PMID 39511134, 2024). "Furthermore, the GSE89961 and GSE97466 datasets in the GEO data confirmed that the PLAU methylation levels in the tumor tissues were reduced compared with those in normal tissues, and GSE33630, GSE35570 and GSE60542 confirmed that the mRNA expression levels were increased." (PMID 35141223, 2022). "Promoter hypomethylation in tumor tissues correlated with overexpression of LAMC2, CTHRC1, CXCL13, FST, SPP1, and PLAU, whereas CDKN2A showed hypermethylation." (PMID 41776121, 2026). "Despite these differences, we believe the genes identified in our study—COL3A1, PLAU, and SPP1—have common roles in ECM remodeling, cell adhesion, and tumor cell migration, processes that are shared across cancer types." (PMID 41465316, 2025). "Recent studies have highlighted the pivotal roles of PLAU and GREM1 in modulating tumor treatment responses." (PMID 41048340, 2025). "PLAU and its receptor PLAUR have been shown to induce a mesenchymal gene expression signature in GBM cells, promoting tumor cell survival and correlating with poor prognosis." (PMID 40835683, 2025). "We, therefore, confirmed the ALDH1A3‐dependent regulation of PLAT, PLAU, and SERPINB2 by RT‐qPCR and visualized the co‐expression correlation of the genes with ALDH1A3 in the patient tumour data." (PMID 37753740, 2024). "PLAU is overexpressed in various cancers, including ESCC, and tumor-secreted PLAU promotes the formation of iCAF via the uPAR/AKT/NF-κB/IL8 pathway." (PMID 39334513, 2024). "This includes tumor growth-inhibiting as well as -activating signals, such as the potential regulation of the ETV4 transcriptional activity by DCN or the PLAU-PLAUR ligand-receptor interaction." (PMID 38200223, 2024). "Our results encompass a range of novel and well-known tumor growth-inhibiting as well as -activating signatures, such as the potential regulation of the ETV4 transcriptional activity by DCN or the PLAU-PLAUR ligand-receptor interaction." (PMID 38200223, 2024). "In clinical samples analysed by TCGA, the expression of 5 genes, CCL20, IL1B, IL24, PLAU and SEMA7A, was significantly higher in the primary tumour than in solid normal tissue, whereas that of CITED2 was lower." (PMID 38363001, 2024). "Specifically, in TNBC cells we find that ALDH1A3 can transcriptionally regulate PLAT, PLAU, and SERPINB2; however, considering both the cell line and patient tumour data, the strongest overall evidence was between ALDH1A3 and PLAT/tPA." (PMID 37753740, 2024). "Bioinformatics analysis and sequence alignments performed in our laboratory proposed that miR-3174 can target many influential tumor-promoting genes involved in the pathobiology of GBM, including CD44, PLAU, MDM2, CDK6 and RHOA." (PMID 37298284, 2023). "Among the positively correlated gene sets, PLAU and LAMC2 were more strongly expressed in tumour samples than in normal samples." (PMID 37325056, 2023). "Significant changes have been detected in the tumor microenvironment pathway including genes MMP19, MMP24, and CSF2, as well as PLAU, BCL2, TIAM1 and Rac1." (PMID 38003292, 2023). "EPCAM, PLAU and THBS1 were shown to be induced within TDLNs secondary to the afflux of tEV from primary tumor, and are involved in tumor cell recruitment and extra-cellular matrix remodeling." (PMID 38074683, 2023). "Further, we also demonstrated that miR-3174 downregulates multiple tumor-promoting genes (CD44, MDM2, CDK6, RHOA and PLAU) and all of these have been reported to have an important role in the development of various malignancies, including GBM." (PMID 37298284, 2023).
tumor (continued). "AHCY-deficient SW480 cells exhibit significant upregulation of genes important for the tumor microenvironment pathway, such as MMP19, MMP24, and CSF2, as well as upregulated activation of PLAU and BCL2." (PMID 38003292, 2023). "The tools predicted several tumor-promoting genes as a potential target of miR-3174 including CD44, CDK6, MDM2, RHOA and PLAU." (PMID 37298284, 2023). "At first, tumor cells were shown to interact with TAM subtypes, such as the ANXA1-FPR3, PLAU-PLAUR, and MDK-LRP1 pairs between the Ductal_cell_A and Macro_SPP1_APOE cell types in PDAC." (PMID 38002057, 2023). "miR-3174 downregulated the expression of multiple tumor-promoting genes including CD44, MDM2, RHOA, PLAU and CDK6." (PMID 37298284, 2023). "PLAU and MMP14 were highly expressed in both tumor cells 3 and CAFs but were also consistently detected in TAMs and tumor cells." (PMID 37007745, 2023). "Of these genes, ITGA5, PLAU, PLAUR, SERPINE1, TGFB1, and VEGFC were significantly highly expressed in tumor compared to normal tissues." (PMID 36425786, 2022). "As expected, ITGA5, PLAU, PLAUR, SERPINE1, TGFB1, and VEGFC were consistently overexpressed in tumor tissues compared to normal tissues (log2FC > |1| and p ≤ 0.01)." (PMID 36425786, 2022). "While bulk tumor analysis represents a limitation of our study, nonetheless we identified significant upregulation of key TSK signature genes, in particular PLAU, MMP1 and MMP10, ITGA5 in MET vs. PRI- and PRI+ vs. PRI-." (PMID 35480116, 2022). "Lastly, since highly downregulated DEGs such as PLAU, CTGF and CRYAB are known to promote angiogenesis in cancer, the in vivo tumor-suppressive effects of MARK3 were investigated via a mouse xenograft experiment using MARK3-inducible OVCAR3 cells." (PMID 35017636, 2022). "In tumor tissues, PLAUR can activate extracellular matrix proteolytic enzymes outside the cells by binding to urokinase-type plasminogen activator (uPA or PLAU), its ligand." (PMID 35864968, 2022). "Growing evidences indicate that down-regulation of PLAU and PLAUR attenuate the ability of tumor cells to invade and metastasize, but what triggers the regulation remains a critical question." (PMID 35087738, 2021). "Consistent with our results, previous studies have also confirmed that PLAU regulates ECM remodeling of the extracellular matrix, affects cell adhesion, and promotes tumor metastasis." (PMID 33574243, 2021). "The MIR4435-2HG- and ELFN1-AS1-associated ceRNA subnetworks affected and regulated the expression of the COL5A2, LOX, OSBPL3, PLAU, VCAN, SRM, and E2F1 target genes and were found to be related to prognosis and tumor-infiltrating immune cell types." (PMID 33750326, 2021). "In summary, PLAU was not only a prognostic marker of ESCC, which promoted tumor cell proliferation and migration, but also promoted the formation of inflammatory CAFs by the PLAU secreted by tumor cells." (PMID 33574243, 2021). "The comparison of gene expressions in tumor and normal tissues revealed that CTSG and LCORL were downregulated, while TNFRSF4 and PLAU were upregulated in OSCC tissues." (PMID 34497859, 2021). "RNA-seq data also demonstrated that several genes related to adoptive immune systems which have pro-tumor action, such as TGFβ2, TGFBI, TGFBR1, TGFBR3, PLAU, IL-1β, and IL-33 are higher in Pn-positive cells than Pn-negative cells." (PMID 34680221, 2021). "EV-miR-15a, miR-181b, miR-320c and miR-874 from liver stem-like cells inhibit the migration and tube formation of tumor-derived endothelial cells and potential tumor angiogenesis by downregulating FGF1 and PLAU." (PMID 32503543, 2020). "We then performed qRT-PCR in SFE-treated ESCC cells and ground tumor lumps from the previous xenograft tumor assay, verifying that the expression of CXCL10, TNFAIP3, INHBA, and PLAU was indeed controlled by SFE in ESCC." (PMID 33374641, 2020).
tumor (continued). "CXCL5, ELN, JUN, and FGFR4 were highly expressed in normal tissues, while PLAU, RNASE7, JAG1, SPP1, and TNFRSF18 were highly expressed in tumor tissues." (PMID 32699529, 2020). "We performed meta-analysis on 8 microarray studies and identified six significantly up- (PLAU, FN1, CDCA5) and down-regulated (CRNN, CLEC3B and DUOX1) genes which were subsequently quantified by RT-qPCR in 100 HNSCC patient margin and core tumour samples." (PMID 31443700, 2019). "Nevertheless, poorly differentiated cell lines mimicked upregulated expression of genes (in tumours) such as CAV1, COL4A1, and novel candidates such as TSPAN5, TENM2, C15orf48, PLAU, AHNAK2, FAM129A, PLAU and platelet-specific phosphofructokinase (PFKP)." (PMID 30176945, 2018). "In our previous study, we showed that miR-193a-3p promotes Pa chemoresistance in BCa cells in tumor xenografts of nude mice by repressing three of its targets in the tumor tissues: SRSF2, PLAU and HIC2." (PMID 25991669, 2015). "Several common target genes in the networks were down-regulated in both wt and mt tumor cells, such as ITGA5 and S100A2 (adhesion and migration), SERPINE1 (angiogenesis), CDKN1A (growth arrest), and PLAU and SERPINE5 (proteolysis)." (PMID 24069219, 2013). "The identified genes are involved in drug transport and detoxification (ABCB1, DNAJC15, GSTP1, RAB6C), DNA damage repair (BRCA1) as well as tumor cell proliferation/invasion (APC, CDH1, ESR1, HIC, PLAU, RASSF1, SULF2, TGM2)." (PMID 20544021, 2010). "The connection including TGM2, IL1B, and PLAU and the connection including RAB25, SNAI1, and CDH1 were suggested to be related to tumor invasion by IPA." (PMID 20142997, 2010). "Relative mRNA expression levels were significantly higher in tumor than in healthy samples for FN1, MMP1, PLAU and SPARC (Wilcoxon test for paired data, p ≤ 0.002)." (PMID 19835631, 2009). "The results showed that IGF2BP2, PLAU, and CEP55 were found to be statistically significantly higher expressed in tumours than in normal samples, while CMYA5 was statistically significantly lower expressed in tumours." (PMID 40762677, 2025). "Nevertheless, our analysis of the TCGA data has demonstrated that COL3A1 and SPP1 show significant differential expression across AJCC tumor staging, and COL3A1 and PLAU show significant differences in T-staging, while COL3A1 and SPP1 are differentially expressed in N-staging." (PMID 41465316, 2025). "These methods allow for a more granular understanding of gene expression within individual cell types in the tumor and could clarify whether COL3A1, PLAU, and SPP1 are differentially expressed across various cell types within the same tumor." (PMID 41465316, 2025). "The higher expression levels in the tumour of IGF2BP2 and PLAU were validated by qRT-PCR." (PMID 40762677, 2025). "Therefore, if PLAU expression due to P. gingivalis infection is down‐regulated, the risk of death in patients with advanced cancer may be reduced to that in patients with T1‐2 tumours or without lymph node metastases." (PMID 38363001, 2024). "Assessment of the methylation levels of a couple individual CpG methylation sites in the TSS and expression of PLAU in patient tumours did not reveal negative correlations with PLAU expression (right)." (PMID 37753740, 2024). "PLAU promotes ESCC proliferation and tumor growth by activating the MAPK pathway." (PMID 39149564, 2024). "Plasminogen activator, urokinase (PLAU) and cyclophilin A (PPIA), which promote EMT in tumor cells and fibrosis in CAFs34–36, were enriched in signaling nodes between myCAFs:cancer cells and monocyte/macrophages:cancer cells in the older cohort, supporting the EMT ARPs previously observed." (PMID 39483921, 2024). "Interestingly, several extracellular matrix protein genes predominantly expressed in CAFs, such as PLAU, MMP14, were also highly expressed in the mesenchymal-like tumor population (Tumor cells 3)." (PMID 37007745, 2023).
tumor (continued). "Interestingly, we found PTHLH derived from tumor cells can target macrophages and regulate the expression of CCL13, PLAU and ICAM1, resulting the phenotype of TAM_c1." (PMID 38044943, 2023). "Therefore, these six tumor-related genes (ITGA5, PLAU, PLAUR, SERPINE1, TGFB1, and VEGFC) were considered as prognostic biomarkers for HNSCC." (PMID 36425786, 2022). "For discrimination of the normal and tumour sampling zones, we were able to derive an effective gene-based classifying model for molecular abnormality based on a panel of eight genes (MMP1, MMP12, MYO1B, TNFRSF12A, WDR66, LAMC2, SLC16A1 and PLAU)." (PMID 35327656, 2022). "Collectively, these results suggest that PLAU may be an independent biomarker for predicting the outcomes of HNSCC patients and potentially contribute to tumour immunosuppression either in concert with or via TNFRSF12A." (PMID 35327656, 2022). "In addition to the abnormal expression during tumor progression, PLAU and PLAUR are also found involved in complicated tumor invasion and cell migration." (PMID 35087738, 2021). "We found that PLAU promotes ESCC proliferation and tumor growth by activating the MAPK pathway." (PMID 33574243, 2021). "These collectively suggest that PLAU might server as a significant TF promoting PTC progression, while EGR2 might be a tumor suppressor." (PMID 29351231, 2018). "Strikingly, when integrating the transcriptome under HO-1 modulation with the HO-1 interactome, a framework of four main molecular pathways arose as the foundation for the regulation of the tumor cell protrusive forces: ANXA2/HMGA1/POU3F1; NFRSF13/GSN; TMOD3/RAI14/VWF; PLAT/PLAU." (PMID 28032857, 2016). "In addition to SPINT2, four further genes (CDH1, PLAU, IGFB3 and MT1G) had previously been reported to undergo promoter region hypermethylation in RCC tumours." (PMID 18195710, 2008). "All these molecules are known to be involved in cancer process, some being identified as tumour suppressor genes (e.g. GPR54 and CLDN23) and others related to angiogenesis (e.g. CXL1 and EDNRA) or cell migration capacities (e.g. PLAU)." (PMID 17406368, 2007). "Moreover, the plasminogen activator-urokinase (PLAU) and cyclophilin A (PPIA) signaling nodes, which promote EMT in tumor cells and fibrosis in CAFs35–37, were enriched between cancer epithelial cells (receptors) and both monocyte/macrophage and CAFs (ligands) in the older cohort." (PMID 41188599, 2025). "Interestingly, PLAU protein expression in PDAC was associated with gender but not age, T classification, M classification, TNM stage, tumor size, and vascular and nerve invasion." (PMID 36937875, 2023). "In this study, pBD2 showed anti-tumor potential by upregulating the expression of PTEN and downregulating the expression of SPRY2 and PLAU, and pBD2 was also shown to promote cell proliferation by upregulating the expression of CDC25A, E2F2, and PTGS2, which perhaps might lead to tumorigenesis." (PMID 36077151, 2022). "Therefore, the upregulation of PLAU in CTC-clusters may be a mechanism to enhance CTC survival in circulation and might suggest a role in tumor cell clustering." (PMID 34502201, 2021). "In addition, expression of molecules involved in ECM remodeling such as several metalloproteinases (MMP2, MMP9, MMP10 and MMP13), serine protease (PLAU) collagens, fibronectins and integrins indicate that functional EMT transition and metastasis take place within the tumor microenvironment." (PMID 34946170, 2021). "Hence, our study revealed a significant correlation between a high risk score and immunosuppression and its association with the growth and differentiation of B and T cells, and high expression of PLAU, APP and EGFR were the main factors of tumor immunosuppression." (PMID 33232279, 2020).